TRBJ2-1 (T cell receptor beta joining 2-1)
Description:
J region of the variable domain of T cell receptor (TR) beta chain that participates in the antigen recognition. Alpha-beta T cell receptors are antigen specific receptors which are essential to the immune response and are present on the cell surface of T lymphocytes. Recognize peptide-major histocompatibility (MH) (pMH) complexes that are displayed by antigen presenting cells (APC), a prerequisite for efficient T cell adaptive immunity against pathogens. Binding of alpha-beta TR to pMH complex initiates TR-CD3 clustering on the cell surface and intracellular activation of LCK that phosphorylates the ITAM motifs of CD3G, CD3D, CD3E and CD247 enabling the recruitment of ZAP70. In turn ZAP70 phosphorylates LAT, which recruits numerous signaling molecules to form the LAT signalosome. The LAT signalosome propagates signal branching to three major signaling pathways, the calcium, the mitogen-activated protein kinase (MAPK) kinase and the nuclear factor NF-kappa-B (NF-kB) pathways, leading to the mobilization of transcription factors that are critical for gene expression and essential for T cell growth and differentiation. The T cell repertoire is generated in the thymus, by V-(D)-J rearrangement. This repertoire is then shaped by intrathymic selection events to generate a peripheral T cell pool of self-MH restricted, non-autoaggressive T cells. Post-thymic interaction of alpha-beta TR with the pMH complexes shapes TR structural and functional avidity.
Synonyms: TRBJ21; TCRBJ2S1
Gene: T-cell receptor joining (J) gene on chromosome 7 (142,796,365 to 142,796,414, forward strand). Ensembl gene ENSG00000211764.
Subcellular location: Cell membrane
Gene Ontology:
Cellular component: plasma membrane
Diseases named in the same sentence as TRBJ2-1 in open-access papers:
TRBJ2-1 is named in the same sentence as 1 disease in open-access papers, as found by Europe PMC text mining. Sharing a sentence is not in itself a finding about the gene and the disease. The quoted sentences say what the papers report.
tumour (1 paper, 2018). "Here we show that the structures of two distinct TCRs (TRAV4+TRAJ21+-TRBV28+TRBJ2-3+ and TRAV4+TRAJ8+-TRBV9+TRBJ2-1+), originating from a polyclonal T-cell repertoire, bind to HLA-B*07:02, presenting a 13-amino-acid-long tumour-associated peptide, NY-ESO-160–72." (PMID 29531227, 2018).